SDC4 (syndecan 4)
Diseases named in the same sentence as SDC4 in open-access papers (continued):
Sharing a sentence is not in itself a finding about the gene and the disease.
tumor (continued). "In both seminomatous TGCTs and NSGCTs, significantly increased expression for syndecan-4 was detected in tumour cells." (PMID 23844358, 2013). "The lower staining of syndecan-4 in tumour cells is significantly correlate, with nodal metastasis, vascular and lymphatic invasion, and disease stage in NSGCTs." (PMID 23844358, 2013). "Notably, NRG1 fusions were identified in a subset of tumours, including recurrent SDC4::NRG1 events, potentially playing key roles in disease progression." (PMID 41914575, 2026). "While SDC4 is well-known for its role in cellular processes such as adhesion, migration, and proliferation, its specific involvement in cell cycle dysregulation in tumor cells remains poorly understood." (PMID 41890271, 2026). "Disruption of the axis through SPHK1 knockdown in CAFs, genetic perturbation of MALL or SDC4 in cancer cells, or adeno-associated virus-mediated SPHK1 or SDC4 knockdown in KPC (KrasLSL-G12D/+; Trp53LSL-R172H/+; Pdx1-Cre) mice significantly reduces PNI and tumor burden." (PMID 42017444, 2026). "In vitro, COL1A1 overexpression in HUVECs increased ANGPTL4, and co-culture with the gastric adenocarcinoma line MKN45 enhanced cancer cell invasion and proliferation, supporting a model in which ANGPTL4 from COL1A1+ ECs engages SDC4 on tumor cells to promote GC progression and spread." (PMID 41154806, 2025). "These experiments could help determine whether SDC4 directly contributes to tumor growth, metastasis, or chemoresistance." (PMID 40416874, 2025). "The silencing of syndecan-4 impaired these processes and reduced the invasive potential of tumour cells, highlighting its contribution to the formation of alternative vascular networks that sustain tumour growth." (PMID 41463344, 2025). "High expression of SYND4 (the gene encoding SDC4) was associated with reduced RFS (HR = 1.38, p = 0.04) in TNBC patients, highlighting its potential role in promoting tumor progression through matrix-mediated mechanisms." (PMID 40940762, 2025). "SDC4 expression was increased after lung injury and tumor cell seeding." (PMID 39400975, 2024). "Thus, our data strongly support that the signaling coming from the TME and converging on SDC1 and SDC4 on START tumor cells sustain tumor progression." (PMID 38546390, 2024). "Additionally, Midkine (MDK) released from tumour cells interacted with SDC4, SDC1, NCL, ITGA4, ITGA6 and ITGB1 on immune cluster." (PMID 39187937, 2024). "In addition, SDC4 is also involved in extracellular matrix remodeling, tumor cell metastasis and invasion, angiogenesis, cardiovascular disease, inflammatory response, and muscle regeneration." (PMID 39400975, 2024). "In particular, genes encoding collagen, including COL1A1, COL1A2, COL6A1, and COL6A3, are upregulated in tumor tissue and also highly expressed in late-stage cancer patients; they are predicted to interact with SDC1 and SDC4 in tumor cells to promote the pEMT phenotype of tumors." (PMID 38002057, 2023). "However, the SDC4 expression had significant correlations with tumor differentiation, TNM stage, and lymph node metastasis (P < 0.05)." (PMID 36199068, 2022). "In summary of the present study, our data suggested that TN-C promotes tumor cell metastasis and proliferation, and that this is dependent on syndecan-4 mediated activation of NF-κB signal activation, although the mechanism of which was still unknown." (PMID 35246056, 2022). "Previous studies have suggested that interference with the syndecan-4/α5β1 co-receptor in the cell membrane inhibits normal cell proliferation and enhances tumor cell proliferation; however, the mechanisms responsible for this remain unclear." (PMID 35246056, 2022). "Thus, the binding of TN-C with syndecan-4 induces the activation of NF-κB signaling, and promotes tumor cell metastasis and proliferation." (PMID 35246056, 2022).
tumor (continued). "TN-C has been reported to compete with the binding site of fibronectin with syndecan-4, and this interaction with syndecan-4 partially abrogates the effects of this co-receptor, as well as attenuates the interaction of syndecan-4 with fibronectin, enhancing tumor cell malignancy." (PMID 35246056, 2022). "Syndecan-4 (SDC4) is a transmembrane (type I) heparan sulfate proteoglycan that binds to, and modulates the activity of many extracellular proteins related to cytoskeletal protein binding and fibronectin binding implicated in tumor development." (PMID 36171892, 2022). "MiR-139-5p inhibitor or SDC4 overexpression could restore the suppressive influence of silenced WDFY3-AS2 on tumor growth." (PMID 34051810, 2021). "SDC4 has an anti-migratory, anti-invasive tumor suppressor role." (PMID 34282767, 2021). "The function of SDC4 is highly relevant to tumor development and metastasis." (PMID 33990545, 2021). "Here, we summarize the general role of SDC4 in cell migration and tumor cell motility." (PMID 34282767, 2021). "Sdc-4 may have tension-sensing roles, detecting changes in the cytoskeleton in wound contraction, interactions between tumours and surrounding stromal tissue, tissue fibrosis, cellular adhesion and pre-motile changes in cells." (PMID 33922532, 2021). "Overview of SDC4-dependent migration and SDC4 expression in different tumor cell models." (PMID 34282767, 2021). "There are several mechanisms by which syndecan-4 contributes to tumor cell migration." (PMID 33810567, 2021). "However, it has been also demonstrated, that SDC4 has the potential to act as an anti-migratory/anti-invasive tumor suppressor." (PMID 34282767, 2021). "A network analysis of the abundant proteins in tumor cell extracellular vesicles revealed a large protein cluster surrounding T-complex 1 subunit eta and cell cycle and apoptosis regulator protein 2 with branches to tumor-relevant proteins such as syndecan-4 (red)." (PMID 32737655, 2020). "Similarly, syndecan-4, which is mainly involved in cytoskeletal and membrane reorganization and formation of focal adhesions, inhibits cell migration and tumor activity." (PMID 30027065, 2018). "The expression level of SDC-4 alters significantly during tumor progression and metastasis." (PMID 28703800, 2017). "Indeed, we found that dimerized syntenin-1 interacted with the cytoplasmic domain of syndecan-4 to rescue the tumor suppressor function of syndecan-4." (PMID 27830760, 2016). "Upregulation of syndecan-4 has been noted in some carcinomas and such overexpression may correlate with increased tumor cell proliferation." (PMID 25549223, 2014). "Syndecan-4 present not only in extracellular matrix but also in stromal cells may play a tumour promoting role in TGCTs." (PMID 23844358, 2013). "In this study, the overexpression of syndecan-4 in tumour cells may facilitate the transmission of growth signals in these cells since syndecans are important coreceptors for various growth factors." (PMID 23844358, 2013). "Syndecan-4, an important member of the Syndecan family of transmembrane transporter polysaccharides, is a soluble heparan sulfate proteoglycan widely distributed in multi-system tissue cells showing significant protein changes in various disease states, such as inflammation, trauma, and tumor." (PMID 36506585, 2022). "Besides that, we showed that syndecan-4 has an important role in the hallmarks of cancer, modulating multiple steps of tumor progression, including unlimited cell proliferation, resistance to apoptosis, invasive growth and metastasis, tumor angiogenesis and tumor-associated inflammation." (PMID 33810567, 2021).
tumor (continued). "Because SDC4 has multiple roles in tumor development and progression, targeting SDC4-mediated signaling may be a promising possibility for cancer treatment and drug development; however, the ubiquitous expression of SDC4 would require cancer cell specific targeting." (PMID 34282767, 2021). "However, in different types of cancers, syndecan-1 and syndecan-4 may present the opposite effect, promoting the tumor progression." (PMID 30027065, 2018). "In contrast to SDC1 and SDC2, both SDC3 and SDC4 were undetectable in the healthy epithelium, or the tumour stroma, but could be immunolocalized both subcellularly and on defined portions of the cell surface of neoplastic cells, with a particular concentration in focal plaque-like structures." (PMID 25935541, 2015). "Similarly, syndecan-4, which is mainly involved in cytoskeletal and membrane reorganization during stress fiber formation and focal adhesion in the later stages of fibroblast spreading, inhibits cell migration and tumor activity." (PMID 23705906, 2013). "The co-option of SDC4 for mechanotransduction and SDC1 for immune evasion underscores their contextual specialization within the tumor microenvironment." (PMID 41561769, 2025). "Consistent with emerging evidence, syndecan-4 emerges as a critical mediator of ECM-integrin interplay, facilitating focal adhesion kinase activation and cytoskeletal remodeling that promote tumor invasiveness." (PMID 41561769, 2025). "This study aims to identify novel regulatory targets and signaling pathways that modulate the tumor microenvironment (TME) in HGSOC, focusing on the pleiotrophin (PTN) signaling pathway and syndecan 4 (SDC4) expression as potential biomarkers for prognosis." (PMID 40416874, 2025). "We found that CX3CR1+ macrophages enhanced the expression of the corresponding target tumor inhibitory genes, such as BTG2, EGR2, ERG3, NR0B1, and SDC4, on NR5A1+ tumor cells." (PMID 38658971, 2024). "This empirical verification affirms that both SDC1 and SDC4 play an integral role in promoting EMT in CRC cells, consequently propelling tumor progression and metastasis, a finding consistent with our earlier results derived from enrichment analysis." (PMID 38683136, 2024). "Western Blot analysis of tumor tissue from the mice presented that, in GFP-srGAP2 + SDC4 KD group, srGAP2 phosphorylation level and PKCα membrane translocation were significantly decreased." (PMID 36593959, 2023). "To investigate whether the pEMT biological process is potentially caused by SDC1, SDC4, ITGA2, and ITGA3 expressed by CAFs, we further focused on the correlation between the ligand genes from CAFs as well as from Angiogenic_EC with the abundance of malignant tumor cells undergoing pEMT." (PMID 38002057, 2023). "We found that the key genes, especially SDC1, SDC4, ITGA2, and ITGA3, in malignant cells that interacted with CAFs and Angiogenic_EC were positively correlated with the pEMT score in tumor cells." (PMID 38002057, 2023). "Like SDC4, the CD44 cytoplasmic domain is reported to mediate cell migration through Rac1 and RhoA in human tumor cell lines." (PMID 36735684, 2023). "Based on the mRNA sequencing data, FNRMS cases were accompanied by increased syndecan-4 mRNA expression compared to that in FPRMS cases, suggesting syndecan-4 as a potential tumor driver gene in FNRMS promoting tumorigenesis." (PMID 35128576, 2022). "Investigations have confirmed that the co-receptor of syndecan-4/α5β1 is important for tumor cell adhesion to fibronectin of the ECM, and that interference with this function by TN-C decreases tumor cell adhesion and enhances metastasis and proliferation." (PMID 35246056, 2022). "For tumor cells, CD24 was the most important intrinsic molecular providing a “don’t eat me” signal, meanwhile, SDC4 was the most important receptor for cytokine signaling." (PMID 36172359, 2022).
tumor (continued). "Fusion partners that participate in ROS1 rearrangements include CD74, SLC34A2, SDC4 in addition to GOPC/FIG, which was observed in this patient's tumor." (PMID 30719217, 2019). "To evaluate the expression levels of syndecan-4 in TGCT cell lines, we performed RT-PCR analysis in three tumour cell lines." (PMID 23844358, 2013). "Several membrane PGs, including SDC-1, SDC-4, NRP-1, and CSPG4 can potentially present GAG chains on the surface of tumor cells." (PMID 21658254, 2011). "We noted that T cells with high reactivity toward RCAN1-4 presented significantly greater expression of many tumor-reactive T cell-related genes, most notably CCL20, SDC4, and SPRY1, with greater than twofold greater expression than T cells with low/no response to RCAN1-4." (PMID 41436600, 2026). "Previously, we reported that SDC4 is overexpressed in FNRMS, where it may serve as a tumor driver gene." (PMID 40076757, 2025). "SDC4 also exhibited a significantly higher mRNA expression level in the fusion-negative group, suggesting that SDC4 is a potential tumor driver gene for FNRMS." (PMID 40076757, 2025). "MDK seems to be involved in tumor cell communication through binding several of its receptors, including syndecan 1 (SDC1), SDC4, NCL, and LRP1, and MDK from tumors seems to bind to NCL on macrophages and lymphocytes, though the functional consequences have not been explored." (PMID 40429950, 2025). "Tumor clusters 2, 3, and 5 lacked receptors of tumor progression ligand-receptor MDK - SDC4 and exhibited lower expression of the receptors of MDK - NCL." (PMID 40036264, 2025). "To determine whether the ZFP36L1, SDC4 and p-SMAD3 levels are correlated in OS, we collected 70 patient tumor tissue sections." (PMID 37935976, 2024). "Additionally, TENASCIN was frequently observed in the HAS group, with tumor cells in this group interacting with other cells, including tumor cells themselves, via TNC - SDC1/SDC4 or TNC - ITGA8_ITGB1/ITGAV_ITGB6." (PMID 39267750, 2024). "Although EGFR docking with Sdc4 in the tumor cells is required, cell cycle progression does not depend on EGFR kinase." (PMID 35569509, 2022). "Another study failed to confirm this but instead found syndecan-4 expression to be independent of histological tumour grade and histological tumour type." (PMID 23844358, 2013). "Moreover, we tested several hematopoietic tumor cell lines with various expression levels of VLA-4 and syndecan-4 and suggest that syndecan-4 is a key molecule in adhesion-regulated apoptosis induced by TNIIIA2 administration." (PMID 22216033, 2012). "Additionally, MDK–NCL/SDC2/SDC4 interactions played a central role in CAF interactions with other cells, while CD99–CD99 interactions were widely involved in communications between immune cells and tumor cells." (PMID 40260248, 2025). "Given the multitude of syndecan-4-mediated cellular functions with relevance to tumor progression, it is not surprising that the expression of syndecan-4 is dysregulated in a number of malignant diseases, highlighting its importance as a pathogenesis factor and diagnostic marker." (PMID 33810567, 2021). "Besides Pmp22, it is highly possible that other RUNX1/3 targets, such as SDC4, ERN1, and/or MBP, might be involved in tumor formation." (PMID 31032403, 2019). "In contrast, the stromal expression of syndecan-4 in NSGCTs, which are more aggressive in general, is not important for tumour cells dissemination and this may be only regulated by lower expression of syndecan-4 in tumour cells that directly affects their migratory ability." (PMID 23844358, 2013).
cancer (77 papers, 2008 to 2026). A tumor composed of atypical neoplastic, often pleomorphic cells that invade other tissues. "SDC1 and SDC4 have been associated with cell signaling and functional properties, while also holding prognostic value in various cancer types." (PMID 41228316, 2025). "The importance of cell regulators such as SDC4 is underscored by the role of such molecules in preventing excessive cellular infiltration, a hallmark of invasive cancer." (PMID 39716457, 2025). "Conversely, cancer-associated fibroblasts communicate with epithelial cancer cells via MDK targeting SDC2/SDC4/NCL on the epithelial cell surface." (PMID 40429950, 2025). "HSPGs, including the SDC1 and SDC4 proteins, have been linked to metabolism, infectious diseases and cancers including BC." (PMID 36152082, 2023). "For example, syndecan 4 is highly expressed in various cancers and is known to activate signaling cascades associated with cancer cell survival." (PMID 37092398, 2023). "Due to their significant role in numerous cellular mechanisms closely associated with cancers, HSPGs, such as SDC4, and HSPG-related genes such as AKT1 and ATM present an exciting target for BC diagnostics and macromolecular drug therapies." (PMID 36152082, 2023). "SDC4 acts as a main endogenous membrane-associated receptor to regulate cell migration, cell adhesion, and cytoskeleton in tumorigenesis and progression, which can be an ideal anti-cancer therapeutic target." (PMID 36199068, 2022). "Syndecan-4 (SDC4) functions as a major endogenous membrane-associated receptor and widely regulates cytoskeleton, cell adhesion, and cell migration in human tumorigenesis and development, which represents a charming anti-cancer therapeutic target." (PMID 33990545, 2021). "In addition, three signal pathways associated with SDC-4 including proteoglycans in cancer (rno05205), cell adhesion molecules (rno04514), ECM-receptor interaction (rno04512) were found." (PMID 29033837, 2017). "Elevated levels of soluble syndecans, particularly SDC1 and SDC4, have been correlated with adverse outcomes in various cancer types." (PMID 40694191, 2025). "Literature has revealed that high expression of SDC4 is an unfavorable biomarker for various cancer types, including ER-negative breast cancer." (PMID 41228316, 2025). "Cell surface heparan sulfate proteoglycans (HSPGs), namely, syndecan-1 (SDC1), SDC2, and SDC4, are involved in cancer progression, metastasis, and regulate extracellular vesicles (EVs) biogenesis, including the microvesicles (MVs)." (PMID 40940401, 2025). "SDC4 is a cell surface proteoglycan that regulates cancer progression and has a positive correlation with TGF-β signaling pathway." (PMID 37935976, 2024). "Syndecan-4 is an emerging target for cancer treatment, and several cancer therapeutics have been found to downregulate it like trastuzumab (humanized anti-HER2 monoclonal antibody) and panitumumab (human anti-EGFR monoclonal antibody)." (PMID 38106420, 2023). "Hopefully, once a more specific inhibitor of syndecan-4 is available, it can be multi-purposed for cancer and CD treatment." (PMID 38106420, 2023). "The results showed that srGAP2 phosphorylation and SDC4-mediated PKCα recruitment were more obvious in cancer tissues compared with para tissues." (PMID 36593959, 2023). "For instance, increased expression of COL6A1, SDC4, FRAS1, AGRN, and COL4A2 has been observed in different cancer types and reported to be associated with metastasis and poor outcomes in patients." (PMID 37987316, 2023). "Among the top CellChat interactions, we identified MDK from CAFs targeting SDC2/SDC4/NCL of cancer cells." (PMID 36352420, 2022). "For cytokines, CCL5 is highly expressed in CD8 + T cells, NK Cells, NKT Cells, CD4 + T Memory Cells, Plasma Cells, and Langerhans Cells and strongly interacts with SDC1 and SDC4 in Cancer Cells, affecting cancer progression, development, and the survival." (PMID 36401283, 2022).